IL2 (interleukin 2)
Diseases named in the same sentence as IL2 in open-access papers (continued):
Sharing a sentence is not in itself a finding about the gene and the disease.
cancer (continued). "Cytokines, such as interferon (IFN), interleukin 2 (IL‐2), and interleukin 15 (IL‐15), have been extensively studied in clinical settings of other cancers." (PMID 38037752, 2023). "To date, the only available treatments, such as lipid-lowing agents, immune regulators, antiviral and anti-cancer agents, microRNAs, and combined therapies (e.g., IL-2 and IFN), regulate NK cell activation to inhibit fibrosis-causing factors." (PMID 37239062, 2023). "Recently, several studies combined IL-2 agonists with immune checkpoint therapies to treat cancer and chronic infections in preclinical studies." (PMID 37827864, 2023). "IL-2 administration has been shown to increase CD4+CD25+Foxp3+ Treg numbers in patients with cancer." (PMID 38004268, 2023). "IL-2 was the first recombinantly produced cytokine and remains in use as an immunostimulatory with anti-cancer activity, and it is involved in the activation and growth of T and NK cells." (PMID 37237491, 2023). "High-dose IL-2 treatment is employed to cancer patients with the goal of activating immune cells to destroy cancer cells." (PMID 37741983, 2023). "Despite their immense potential, therapeutic targeting of IL-2 and IL-2R in cancer poses several challenges." (PMID 37516849, 2023). "While interleukin-2 (IL-2), which is approved for its usage in clinical research 9, stimulates the proliferation and survival of NK cells 10, it is down-regulated in cancer patients." (PMID 37056568, 2023). "Cytokines as cancer immunotherapies, such as IL2 and IFNα, can activate and sustain T cell–mediated immunity against cancer cells." (PMID 37546701, 2023). "In targeting IL-2 and IL-2R-mediated pathways, there is a promising approach for treating cancer, and various IL-2 and IL-2R-targeted therapies are currently being developed and tested in clinical trials." (PMID 37516849, 2023). "The burgeoning field of engineered IL-2 for cancer immunotherapy, though in its infancy, carries immense potential, yet it is not devoid of substantial hurdles." (PMID 37516849, 2023). "Although IL-2 has been utilized in immunotherapy, the success of these strategies is variably influenced by the differential expression of IL-2 and IL-2R across diverse cancer types." (PMID 37516849, 2023). "Aerolysin produced by Aeromonas hydrophilia can be made specifically for a cancer cell by adding a specific binding moiety such as interleukin 2 (IL2) to selectively kill cancer cells displaying IL2 receptors." (PMID 37104235, 2023). "Using IL-2 in clinical practice (Aldesleukin) started three decades ago and was considered as the first effective immunotherapy for human cancer." (PMID 36839658, 2023). "Since the emergence of biotechnology, IL-2, as a biological agent for the treatment of cancer, has laid the foundation for the use of other recombinant cytokines to treat tumors." (PMID 36936961, 2023). "Consistent with cancer patient data, responders (increased IL-2) exhibited a significantly lower IRC in CD4 and CD8 T cells compared to nonresponding patients." (PMID 38055623, 2023). "The therapeutic potential of interleukin (IL)-2 in cancer treatment has been known for decades, yet its widespread adoption in clinical practice remains limited." (PMID 37827864, 2023). "Despite these hurdles, engineered IL-2 therapies are poised to become a significant addition to our current arsenal of cancer treatments, provided the obstacles of optimizing effectiveness and minimizing potential drawbacks are carefully navigated." (PMID 37516849, 2023). "It has been shown that combination therapies of IL-15 or IL-2 administration with PD-1/PD-L1 blockade was efficacious in murine cancer and infection models." (PMID 36454338, 2023). "Cytokines themselves traditionally have played a key role in cancer immunotherapy, with some being used as monotherapies (e.g., IL-2, IL-15) or in combinations with monoclonal antibodies (e.g., rituximab) or chemotherapeutics." (PMID 37237491, 2023).
cancer (continued). "IL-2 and IL-2R play pivotal roles in the immunological response against cancer, wielding influence over immune regulation and, thus, cancer therapy." (PMID 37516849, 2023). "Since mice immunized with A549 cells had a significant increase in IL-2 levels, we believe that NK cells in these mice were able to kill cancer cells." (PMID 36674504, 2023). "Overall, the study of IL-2 and its receptor in cancer holds excellent potential for developing new and effective treatments for a wide range of malignancies." (PMID 37516849, 2023). "Several pro-inflammatory cytokines, such as TNF-α, IFN-γ, IL-1, IL-2, IL-6, and IL-12, have been identified to participate in both initiation and progression of cancer." (PMID 37296375, 2023). "The benefits of adoptive NK transfer include the improvement of anti-cancer responses of autologous NK cells through cytokine stimulation, e.g., IL-2, IL-12, IL-15, IL-18 and IFN-γ type I, which enhance the function and proliferation of natural killer cells." (PMID 36980527, 2023). "And there is also a completed phase I/II clinical trial of E6 TCR-T cells combined with lymphocyte depletion and IL2 for patients with metastatic HPV 16-positive cancer that had received prior platinum-based therapy (NCT02280811)." (PMID 36817443, 2023). "Lymphocytes sorted from cancer biopsy samples were expanded by interleukin 2 (IL-2) treatment and reinfused into the patient with subcutaneous IL-2, resulting in an initial outcome of 34% efficacy, with a median response of 4 months." (PMID 36765809, 2023). "We also tested IL2-stimulated NK cells against additional EGFR-positive cancer cells (A549) in presence of ascites and found that malignant ascites suppressed natural cytotoxicity and ADCC." (PMID 37684704, 2023). "IL‐2 plays a critical role in modulating both immune‐effector activities to fight cancer and inducing immune tolerance to prevent autoimmune disorders." (PMID 35246947, 2023). "In cancer models, IL-15 acts in the same manner as IL-2, being less toxic and considered as a promising cytokine for metastasis treatment." (PMID 36839658, 2023). "Antigen-specific activation of anti-CMV CD8pos T cells (CD25pos/ CD107pos) and cytokine secretion (IL-2 and IFNγ) occurred only in the presence of mesothelin-positive cancer cells." (PMID 37568582, 2023). "In the 1980s, Dr. Steven Rosenberg at the National Cancer Institute (NCI) conducted clinical trials in which they administered high doses of IL-2 to patients with advanced cancer, leading to partial or even complete remission of their tumors." (PMID 37256141, 2023). "In particular, these include the recent utilization of chimeric molecules of IL-2 and anti-PD-1 antibody, showing excellent efficacy in preclinical mouse models of cancer and chronic viral infection." (PMID 37827864, 2023). "The GSEA analysis results of BIRC3 observed that various cancer-promoting pathways were enriched in the high expression group including IL2 STAT5 signaling, IL6-JAK-STAT3 signaling, KRAS signaling, PI3K-AKT-MTOR signaling and TNFA signaling via NFKB." (PMID 38130918, 2023). "Due to its powerful effects on cytolytic NK and T cells without causing the expansion of suppressive Treg cells, IL-15 has recently emerged as an alternative to IL-2 in cancer therapy." (PMID 37483629, 2023). "To prepare cancer cell-challenging immune cells, we expanded PBMCs in cell culture using the K-562 cell line in combination with IL-2." (PMID 37925511, 2023). "Other facts presented below demonstrate that IL-2 has a few protumorigenic properties, which makes its use for cancer treatment less encouraging." (PMID 36839658, 2023). "Increased levels of circulating IL-1 (cancer-promoting), IL-2, IL-2 receptors (IL-2R) (cancer-suppressive), IL-4, IL-8, IL-17 (cancer-promoting) and TNF-α have been reported in patients with SSc." (PMID 37681925, 2023).
cancer (continued). "Extensive studies on IL-2 have led to the clinical utilization of this molecule in patients with advanced cancer however this was limited due to the significant systemic side effects associated with its use." (PMID 37580655, 2023). "Studies have shown that the use of IL-2 alone or in combination with other anti-cancer therapies can bring survival benefits to patients with advanced cancer." (PMID 36874629, 2023). "In early studies, IL-2 was co-administered with autologous lymphocytes for cancer treatment or for the amplification of patients’ natural killer (NK) cell and effector T-cell populations." (PMID 37138873, 2023). "Another study demonstrated that PSCA-specific engineered CAR-T cells in combination with interleukin-2 (IL2) eradicate PSCA-expressing cancer cells." (PMID 36969009, 2023). "Emerging evidence supports diverse IL-2 and IL-2R expression levels across different cancer types, potentially shaping their responses to immunotherapy." (PMID 37516849, 2023). "IL-2 alone or in combination with other anti-cancer therapies has brought some survival benefits to advanced cancer patients." (PMID 38001643, 2023). "Lunasin demonstrates immunomodulatory activity against cancer by interacting with the cytokine's interleukin-2 (IL-2) and interleukin-12 (IL-12)." (PMID 37396130, 2023). "Cytokine-based immunotherapy has disappointingly only led to the approval of IFN-α and IL-2 as single agents, and GM-CSF, encoded in oncolytic herpes virus (T-VEC), for the treatment of very few cancer indications." (PMID 37242495, 2023). "Mycobacterium TB can induce the release of inflammatory mediators, e.g., tumor necrosis factor (TNF)-α and interleukin (IL)-1, IL-2, and IL-12, which can be viewed as cancer promotors." (PMID 37817103, 2023). "Our results showed reduced IL-2 secretion in co-cultures of Jurkat and cancer cells, which was rescued upon MTE treatment." (PMID 37649480, 2023). "Interferon-α (IFN-α) and interleukin-2 (IL-2), as representative drugs in clinical practice, are used for the treatment of several malignant tumors with the approval of the US Food and Drug Administration (FDA)." (PMID 37194085, 2023). "Taken together, these results suggest that administration of MARCH5 inhibitor leads to increased efficacies of cancer immunotherapy by IL-2 plus PD-1 blockade." (PMID 37932447, 2023). "In any case, the potent cytotoxic capacity and their expansion by IL-2 agonists make KILR effector CD8+ T cells a promising clinical target in cancer immunotherapy." (PMID 36705564, 2023). "Splenocytes were pre-incubated with Concanavalin A and IL-2 and added to cancer cells in an effector target ratio (E:T) of 10:1." (PMID 37118819, 2023). "Now, recent studies have shown that continuous exposure of CD8+ T cells to high levels of IL-2 leads to lymphocyte exhaustion, losing reactivity to cancer cells, and therefore being unable to exert their cytotoxic function, eventually leading to their death." (PMID 36674504, 2023). "While IL18 alone can prime lymphocytes, IL18 combined with IL2 can promote the proliferation of NK cells, resulting in increased cytotoxicity against cancer." (PMID 38139000, 2023). "Antibodies to EpCAM have been developed for cancer therapy, either as a native monoclonal agent, anti-EpCAM toxin-conjugated antibody, or IL2-conjugated antibody that exhibit promising clinical activity." (PMID 37303738, 2023). "Higher activation and proliferative responses were also observed in the PD-1– memory population in both mice and patients with cancer receiving high-dose IL-2, mirroring the in vitro phenotypes." (PMID 37737264, 2023). "All these consistencies ultimately strengthen that CT is the most important factor in a cancer patient’s survival, and of the IMTs mEHT, fever-inducing interleukin-2 and low-dose ICIs seem to be those, that need further investigations." (PMID 37990076, 2023).
cancer (continued). "The N1 phenotype with high levels of TNF-α, IL-2, IL-4, IL-7, and IL-10 expression induces a cytotoxic effect to cancer cells and hampers cancer cell progression." (PMID 35267547, 2022). "Our results show that the interleukin 15 pathway appeared to increase in activity in SSTR2-high groups in 92.31% of cancers, and the interleukin 2 pathway appeared to increase in activity in SSTR2-high groups in 96.15% of cancers." (PMID 35264912, 2022). "A randomized phase III trial of IL-2 given via the perilymph after oral cavity surgery reported that cancer patients exhibited >25% improvement in OS." (PMID 36338975, 2022). "CAR T-cell IL-2 production and overall glucose consumption are more strongly impacted by the higher level of antigen expression on the cancer cells than by the low antigen expression on healthy cells." (PMID 35903149, 2022). "Combination of IL‐2 with ICI is thus effective for reinvigorating CD8+ T cell responses in patients with chronic infection or cancer." (PMID 35301813, 2022). "IL-2 enhances the effects of T-cell and natural killer (NK) cell activity, allowing the host immune response to target cancers." (PMID 36686754, 2022). "Another challenge with IL-2 is that it can activate both cancer-killing effector T cells as well as immunosuppressive regulatory T cells." (PMID 36135216, 2022). "In the current study, we sought to evaluate the therapeutic efficacy of Salmonella and Alb-IL2 alone or in combination for the treatment of cancer." (PMID 35962391, 2022). "These IL-2 analogs have been described elsewhere and have been tested pre-clinically and some clinically as monotherapies or in combination with cancer vaccines." (PMID 35651800, 2022). "The history of utilizing cytokines as agents for the treatment of cancer initiated in the mid-1990s once the anti-cancer influences of high-dose (HD) IL-2 therapy was first displayed in RCC and other malignancies." (PMID 36510217, 2022). "In summary, Salmonella + Alb-IL2 has potential utility as an off-the-shelf therapy for treating cancer." (PMID 35962391, 2022). "The anti-cancer effect of T cells is greatly enhanced when IL-12 and IL-2 are stimulated simultaneously." (PMID 35680568, 2022). "The higher the number of cancer exosomes, the less the IL-2 production by the surface-attached T-cells." (PMID 35323230, 2022). "Some studies have shown that IL-2 had a profound impact on the development of cancer immunotherapy and had been used in advanced metastatic RCC, resulting in a substantial rate of complete response." (PMID 36159976, 2022). "Cancer immunotherapies, such as administration of the cytokine Interleukin-2 (IL-2), adoptive cell transfer, and the checkpoint modulators CTLA-4 and PD-1, have proved effective in clinical practice." (PMID 35651784, 2022). "CLS has been one of the major limit of IL-2 cancer immunotherapy, since it is a well-known adverse event of systemic administration of IL-2 at high doses." (PMID 36177033, 2022). "Isolation of T cell populations with specific TCRs from the human body, massive expansion by T cell growth factor (IL-2) in vitro and finally reinfusion into patients to achieve cancer elimination are many ways for ACT application." (PMID 36313314, 2022). "IL-2 and IL-15 are effective in supporting cancer immunotherapy, but they also have some side effects." (PMID 36142322, 2022). "We and others have also established unique in vivo manipulating systems including Zoledronate (ZOL) plus interleukin (IL)-2 to remarkably active and expand Vγ2Vδ2 T cells for immune interventions against TB infections or cancers." (PMID 35765887, 2022). "This study demonstrated that human IL2-armed double deleted VV effectively infects and lyses cancer cells, with the high expression of human IL2." (PMID 35799600, 2022). "For instance, in all cancer types, the IL-2 STAT5 signaling pathway was positively correlated with angiogenesis scores, while the DNA repair pathway exhibited the opposite trend." (PMID 35155426, 2022).
cancer (continued). "With the action of cell‐penetrating peptide‐modified nanoparticles, interleukin 2 (IL‐2) and GM‐CSF were efficiently transported into cancer cells." (PMID 39188743, 2022). "We observed that the AP3S1 overexpression was positively associated with many malignant pathways in pan-cancer, such as IL6 JAK STAT3 signaling, IL2 STAT5 signaling, TGF BETA signaling, interferon gamma response, and interferon alpha response." (PMID 35874816, 2022). "A variety of signaling pathways including TNF-α, KRAS, IL-6/JAK/STAT3, IL-2/STAT5, epithelial-mesenchymal transition, oxidative phosphorylation, and mTOR were found to be significantly associated with TRPs in pan-cancer." (PMID 35831825, 2022). "Ontak is an example of an engineered IL-2-diptheria toxin that targets IL-2 receptors on cancer cells into which diphtheria toxin is then delivered." (PMID 36591313, 2022). "There is evidence that the use of IL-2 in cancer treatment induces an inflammatory response system and triggers depressive symptoms." (PMID 36506019, 2022). "Classical and novel anti-cancer immunotherapies (Interferon alpha, Interleukin-2, Immune checkpoint inhibitors, the emerging CAR-T cell therapy) have potential nephrotoxic effects also due to their secondary immune effects." (PMID 35679539, 2022). "Studies have shown that CD3EAP affects the transcription process of rRNA, RNA polymerase activity, and cell proliferation; CD3EAP can also mediate the activation pathway of T cells to produce leukocyte interleukin-2 to inhibit the growth of cancer cells." (PMID 36262474, 2022). "The first approach to cancer treatment was the administration of interleukin-2 (IL-2), capable of stimulating the proliferation of T-lymphocytes." (PMID 35884392, 2022). "g., interleukin (IL)-1 and IL-2) to improve the body's immune response and the survival status of patients with cancer." (PMID 35978996, 2022). "Among the most common AEs of the second cytokine used in the cancer treatment, namely IL-2, are increased body temperature, malaise, nausea, liver enzyme levels elevation and hematological abnormalities." (PMID 36077623, 2022). "After several years of using high-dose IL-2 therapy for cancer treatment, many approaches are under study aiming to improve the therapeutic index of the cytokine." (PMID 36059465, 2022). "IL-15 shares similar functions with IL-2 but has a distinct advantage over IL-2 for cancer immunotherapy due to its minimal binding to the low-affinity IL-2 receptor CD25, resulting in a lack of effect on Tregs." (PMID 35258793, 2022). "IL2 stimulates T cell responses, thus also supporting the concept of other T cell therapeutic approaches to cancer, such as CAR-T cell therapies and checkpoint inhibitors." (PMID 36497356, 2022). "IL-2 has been shown to expand T effector cells for anti-microbial/anti-cancer immunity, while IL-2 can also induce or grow CD4+ CD25+ Foxp3+ regulatory T cells for immune regulation or tolerance." (PMID 35765887, 2022). "IL-2 is one of the key cytokines with pleiotropic effects on the immune system and antitumor activity, and its use is approved for cancer immunotherapy." (PMID 35167620, 2022). "Correspondingly, we find that stroma-targeted stimulation of IL2 pathway in unresponsive tumors restores trastuzumab anti-cancer efficiency." (PMID 36085201, 2022). "When considering desired IL-2 levels produced by CAR T-cells in patient treatment, IL-2 production can be mostly attributed to and designed around cancer cells in isolation as healthy cell antigen expression does have a significant impact." (PMID 35903149, 2022). "In cancer-causing mouse models (B16F10 and CT26), the probiotic strain was combined with IL-2 therapy." (PMID 36263037, 2022).